PPARA (peroxisome proliferator activated receptor alpha)
Diseases named in the same sentence as PPARA in open-access papers (continued):
Sharing a sentence is not in itself a finding about the gene and the disease.
renal fibrosis (continued). "This study aimed to verify the hypothesis that lactate exacerbates renal fibrosis by inhibiting the PPARα/FAO pathway." (PMID 41808346, 2026). "The results of this study conclude that defects in renal PPARα signaling during aging aggravates renal fibrosis development and that targeting PPARα may be useful for preventing age-associated CKD." (PMID 36499760, 2022). "Moreover, PPARα/β activator MHY2013 can significantly increase the expression of FAO-associated genes and prevent renal fibrosis during aging." (PMID 35517820, 2022). "A previous study has confirmed that the level of miR-155 is aberrantly increased during kidney senescence, and antiaging calorie restriction, a powerful antiaging regimen, can downregulate miR-155 level to restore PPARα expression and thus attenuate renal fibrosis during senescence." (PMID 35361048, 2022). "Furthermore, the link between PPARα downregulation and lipid accumulation has previously been described and was shown to be directly related to the development of renal fibrosis." (PMID 34431499, 2021). "Statins may synergistically activate PPARα alongside fenofibrate, and PPARα-dependent reductions in renal fibrosis have been observed following statin treatment in preclinical models." (PMID 35222262, 2021). "Mir-181a-5p has been found to downregulate lipid metabolism regulator PPARα and is in silico predicted to downregulate MAT2A, TIMP3, and LGSF11; miR-451 downregulates YWHAZ and CAB39, which could be implicated in renal fibrosis and mesangial hypertrophy." (PMID 32849923, 2020). "PPARα transcriptionally upregulates many genes involved in FAO, and aged Ppara–/– mice had worsened kidney fibrosis, suggesting that reduced FAO may be linked mechanistically to aged-induced renal fibrosis." (PMID 38516886, 2024). "RNA sequencing and Western blot confirmed that UUO mouse kidney tissues exhibited lactate accumulation, downregulation of the PPARα/FAO pathway, lipid accumulation, and aggravated renal fibrosis." (PMID 41808346, 2026). "ZGP and YGP inhibited renal fibrosis and relieved the decrease in glucose consumption through transcriptional regulatory network of HIF1A and PPARA." (PMID 40417738, 2025). "In this study, we observed that ZGP, YGP, and its components modulated PPARA and its downstream genes, PDK4, to influence renal fibrosis and glucose metabolism." (PMID 40417738, 2025). "The remaining signalling pathways mediating renal fibrosis are STING/TBK1, IL-4Ra/STAT6, Jmjd3/IRF4, STAT6/PPARα, SETD7, NKT/IL-4, BRP-39, STAT-1/TREM-1, MMP-9/Akt, adiponectin/APK, and JAK3/STAT6." (PMID 39445007, 2024). "The kidney is a metabolically active tissue that uses fatty acids (FA) as a major energy source, PPARα, a key transcription factor of the fatty acid oxidation (FAO) pathway, can ameliorate the development of renal fibrosis." (PMID 35222033, 2022). "Collectively, this study uncovered a previously unrecognized function of canagliflozin in FTO in the autophagy modulation through the regulation of SQSTM1 mRNA stability in the renal tubular STAT6/PPARα/FAO axis and renal fibrosis." (PMID 36685533, 2022). "In this study, we focused on the FAO in renal fibrosis, and we identified metabolic enzymes(CPT1A) and transcription regulators (PGC1α, PPARα) of FAO, which indicated that Hypo-EVs can reverse fatty acid metabolism disorder in fibrotic kidney caused by I/R." (PMID 35526054, 2022). "For example, treatment with miR-9-5p was shown to reverse the downregulation of the expression of PPARα and PGC1A and FAO-related enzymes in a mouse model of UUO, further protecting against renal fibrosis." (PMID 35517820, 2022). "Impairment renal PPARα signalling decreased activity of the FAO pathway and aggravated renal fibrosis development." (PMID 35526054, 2022). "Similar results were observed after treatment with BAY PP1, a new PPARα agonist, in UUO and 5/6 nephrectomy models of renal fibrosis." (PMID 35517820, 2022).
renal fibrosis (continued). "PPARα is highly abundant in proximal tubular cells and reduced proximal tubular PPARα expression contributes to the impairment of FAO which promotes renal fibrosis." (PMID 35222262, 2021). "Suppression of the rate-limiting, PPARα-responsive peroxisomal enzyme, Acox1, has been described in experimental renal fibrosis and after treatment of tubular epithelial cells with TGF-β, a phenomenon reversed by the PPARα agonist fenofibrate." (PMID 35222262, 2021). "Pharmacological PPARα and/or PPARβ/δ modulation thus offers an attractive means of promoting FAO to oppose renal fibrosis, 41 with potential for translatability to human AKI and CKD." (PMID 34849404, 2021). "We further assessed fibrotic lesions and found that there was a negative correlation between CPT1A or PPARα expression and renal fibrosis." (PMID 39438470, 2024). "Peroxisome-proliferator-activated receptor-a (PPARα) acts together with PGC-1α to regulate FAO, and previous studies revealed that the PPARα agonist fenofibrate could effectively improve renal fibrosis." (PMID 35455432, 2022). "Indeed, miR-21 efficiently decreases PPARα expression, impairs FAO, and aggravates renal fibrosis development during aging." (PMID 35517820, 2022). "Here, we found that canagliflozin significantly upregulates SQSTM1/P62, promoting PPARα-mediated FAO by inducing autophagy-dependent STAT6 degradation both in TGF-β1-treated HK2 cells and in unilateral ureteral occlusion (UUO) and ischemia–reperfusion (I/R) renal fibrosis mouse models." (PMID 36685533, 2022). "Although HIF-1α was found to be involved in fibrosis, the relationship among miR-21, PPARα and HIF-1α in aging-related renal fibrosis has not been reported." (PMID 32963130, 2020).
prostate carcinoma (45 papers, 2008 to 2026). A carcinoma that arises from epithelial cells of the prostate gland. "Our data suggest that PFAS exposure has a synergy with an HFD to activate PPARα altering the cell metabolome, which shifts carcinogenic risk in normal cells while driving cancer progression in prostate cancer cells." (PMID 34836157, 2021). "In prostate cancer, it regulates lipid metabolism via miRNA-mediated PPARA signaling, influencing neutral lipid accumulation." (PMID 40906132, 2025). "First, we examined PPARα stability using a cycloheximide chase assay in DU145 prostate cancer cells stably expressing vector (DU145pCIP) or PIM1 (DU145hPIM1)." (PMID 38097734, 2024). "Collectively, these data indicate that activation of PPARα downstream of PIM1 is essential for LD accumulation and underscore the role of LD accumulation in mediating PIM1-associated cell proliferation in prostate cancer." (PMID 38097734, 2024). "In LNCaP human prostate cancer cells, the PPARα (NR1C1) agonist fenofibrate was able to mitigate against the androgen receptor agonist‐evoked increase in TMPRSS2 expression." (PMID 32358833, 2020). "This novel PPARα/ROS-independent mechanism of fenofibrate cytotoxicity opens perspectives for elaboration of new metronomic strategies of prostate cancer treatment that would target the energy metabolism/drug-resistance of cancer cells." (PMID 30641904, 2019). "The gene regulation of lipid metabolism by peroxisome proliferator-activated receptor alpha (RPARalpha) has been reported to be a candidate in prostate cancer development, that function by regulating gene expression through DNA methylation." (PMID 31040866, 2019). "Sub-network analysis of the signaling pathway proves that PPARA gene network wiring is significantly altered in prostate cancer." (PMID 28084397, 2017). "The results further reiterate the importance of PPARA in distinguishing prostate cancer samples from the normal ones." (PMID 28084397, 2017). "Keratan sulfate biosynthesis,the pathway of regulation of actin cytoskeleton, the pathwaysassociated with prostate cancer and small cell lung cancer were notidentified as hepatic PPARα independent but as WY14643dependent ones in intestinal study." (PMID 21811494, 2011). "Insubcutaneously implanted human pancreatic cancer cells grown in mice, as wellas in human prostate cancer, PPARα expressionwas detected not only in the tumour cells, but also in the new invadingmicrovessels." (PMID 19043612, 2008). "Additionally, the aberrant overexpression of PDHA1 in AnoR prostate cancer cells upregulates PPARA and AIFM2 expression through nuclear translocation, collectively suppressing ferroptosis and promoting metastasis." (PMID 41724793, 2026). "PPARA, in turn, activated the transcription of apoptosis-inducing factor mitochondria-associated 2 (AIFM2), whose upregulation inhibited ferroptosis in AnoR prostate cancer cells." (PMID 41724793, 2026). "Finally, targeting PIM1 or PPARα signaling was sufficient to abrogate the proliferative and survival functions associated with LD accumulation or PIM1 in prostate cancer." (PMID 38097734, 2024). "Moreover, targeting PIM1 or PPARα signaling using genetic or chemical means abrogates the proliferative and survival advantage associated with LD accumulation and PIM1 induction in prostate cancer." (PMID 38097734, 2024). "Together, our study suggests that alterations in cell metabolism downstream of PPARα activation by PFAS and HFDs may underpin the increased prostate cancer risk observed in PFAS-exposed men." (PMID 34836157, 2021). "Past work has established links with cancer for some of these genes; for example, NCOR1, a nuclear co-repressor with 14 isoforms detected, has been postulated to regulate retinoic acid and thyroid hormone receptor protein levels and to disrupt PPARα/γ signaling in prostate cancer." (PMID 26939613, 2016).
prostate carcinoma (continued). "Here, we show peroxisome proliferator-activated receptor α (PPARα) acts downstream of PIM1 kinase to accelerate LD accumulation and promote cell proliferation in prostate cancer." (PMID 38097734, 2024). "In the present study the expression of AGO2, SSB, and NF2 is downregulated in early-stage cancer and upregulated in advance-stage cancer; whereas PPARA was overexpressed and DICER1 was inhibited across all stages of prostate cancer." (PMID 31756185, 2019). "PPARα and PPARβ/δ expressions are detected among normal prostate, BPH, and prostate cancer tissues, while expression of PPARγ was observed in prostate cancer but not in normal prostate and BPH." (PMID 31212954, 2019). "Furthermore, some pathways such as keratan sulfate biosynthesis, the pathway of regulation of actin cytoskeleton, the pathways associated with prostate cancer and small cell lung cancer were not identified as hepatic PPARα-independent but as WY14643-dependent ones in intestinal study." (PMID 21811494, 2011). "In the present study, upregulation of PPARα signaling contributed to LD accumulation following PIM1 induction, which may promote proliferation of prostate cancer cells." (PMID 38097734, 2024). "Moreover, blocking PPARα signaling using a specific inhibitor, GW6471, was sufficient to reduce LD accumulation and abrogate the effects of PIM1 induction prostate cancer proliferation." (PMID 38097734, 2024). "It demonstrates that PPARα-/ROS-dependent signaling systems are not involved in cell reactions to FF, even though the inhibition of DU145 proliferation by PPARα inhibition shows the significance of PPARα for the welfare of prostate cancer cells." (PMID 30641904, 2019). "Unfortunately, as yet,there is a little clinical evidence to support these actions, apart from thepromising results with the PPARγ ligand troglitazone in liposarcoma and prostate cancer previouslymentioned.Clinically, PPARα and γ ligands do not appear to bestrong antiangiogenic drugs." (PMID 19043612, 2008). "Given that LD accumulation in our experimental setting occurred through the GSK3β-PPARα signaling axis downstream of PIM1, we hypothesized that blocking PPARα could counteract the known positive effect of PIM1 induction on cell proliferation in prostate cancer." (PMID 38097734, 2024).
Parkinson disease (44 papers, 2008 to 2026). A progressive degenerative disorder of the central nervous system characterized by loss of dopamine producing neurons in the substantia nigra and the presence of Lewy bodies in the substantia nigra and locus coeruleus. "Fenofibrate (PPARα agonist) reduced the depressive-like behavior and memory deficits in rotenone-lesioned rats developing Parkinsonism." (PMID 41301903, 2025). "Recent Studies have demonstrated that PPARα holds potential as a therapeutic target for Parkinson's disease, which is a chronic neurodegenerative disorder of the central nervous system characterized by loss of dopaminergic neurons." (PMID 25705219, 2015). "Fenofibrate and PPARα had neuroprotective effects in a toxin-induced model of Parkinson's disease, and these effects were mediated in part by decreased oxidative stress." (PMID 25705219, 2015). "Similarly, other authors demonstrated involvement of PPARα by CA, showing neuroprotective effects on a model of Parkinson’s disease (PD)." (PMID 39684490, 2024). "The role of PPARα in neurodegenerative disorders is also relevant for Parkinson’s disease (PD), given the anti-inflammatory and neuroprotective effects and the role played by neuroinflammation in dopaminergic cell death, which has been demonstrated in different animal models of PD." (PMID 35625650, 2022). "The activation of PPARα exhibits protection by suppressing oxidative stress in multiple animal models including alcoholic liver disease, diabetic retinopathy, and Parkinson's disease." (PMID 30911353, 2019). "Additionally, diminished levels of PPARα and NURR1—proteins essential for neuronal survival—along with elevated expression of IBA1 and GFAP, markers of microglial activation and astrocytic gliosis, respectively, are associated with the pathogenesis of Parkinson’s disease." (PMID 40422188, 2025). "This review focuses on the emerging role played by PPARα in neuropsychiatric and neurodevelopmental disorders, including depression, schizophrenia, and autism spectrum disorder (ASD), and in neurodegenerative diseases, such as Alzheimer’s and Parkinson’s disease." (PMID 35625650, 2022).
rheumatoid arthritis (44 papers, 2010 to 2025). A chronic, systemic autoimmune disorder characterized by inflammation in the synovial membranes and articular surfaces. "Endogenous and pharmacological PPARα agonists have been investigated for their potential therapeutic applications in several chronic inflammatory disorders (e.g., rheumatoid arthritis)." (PMID 35832492, 2022). "PPARα activation with fenofibrate was first reported in a clinical case study for the treatment of rheumatoid arthritis." (PMID 32785018, 2020).
dilated cardiomyopathy (39 papers, 2013 to 2025). Cardiomyopathy which is characterized by dilation and contractile dysfunction of the left and right ventricles. "Intriguingly, treatment of 3-month-old TazKD mice with the pan-PPAR agonist (primarily PPARα), bezafibrate, via supplementation in the diet (0.05% weight/weight) for 4 months, prevented the development of dilated cardiomyopathy and systolic dysfunction." (PMID 33041869, 2020). "Moreover, the Gene Expression Omnibus (GEO) dataset GSE57338 revealed that PPARA expression is downregulated in human hearts with HF, especially related to dilated cardiomyopathy." (PMID 36894670, 2023). "Importantly, PPARα downregulation is also observed in clinical hypertrophic CHF, although it should be noted that increased PPARα expression is reported in human dilated cardiomyopathy, highlighting potential stress-dependent differences in cardiac PPARα signalling." (PMID 32575797, 2020).
alcoholic liver diseases (38 papers, 2009 to 2026). A disorder caused by damage to the liver parenchyma due to alcohol consumption. "It was confirmed that EPPH was involved in fat metabolism in hepatocytes by regulating PPARα in an alcoholic liver disease animal model." (PMID 36101395, 2022). "For instance, PPARα is downregulated in alcoholic liver disease as well as after liver transplantation." (PMID 22645601, 2012). "Therefore, activation of these enzymes by PPARα agonists can accelerate the degradation of various fatty acids, thus preventing and treating alcoholic liver disease." (PMID 35003311, 2021). "PPARα is known to regulate fatty acid metabolism (which is increased during stellate cell activation) and may be a therapeutic target to ameliorate alcoholic liver disease, which may proceed through activation of hepatic stellate cells." (PMID 26217230, 2015). "However, the role of PPARα in pathogenesis of alcoholic liver disease (ALD) remains largely unknown." (PMID 22208561, 2011). "However, the role of PPARα in alcoholic liver disease is largely unknown." (PMID 22208561, 2011).
asthma (36 papers, 2007 to 2025). "PPARα was expressed in eosinophilic granulocytes and downregulated in allergic inflammation and eosinophil activation in vitro and in murine models of asthma." (PMID 39451206, 2024). "Fenofibrate, known as a lipid-lowering agent and a peroxisome proliferator-activated receptor-alpha (PPARα) agonist, decreases experimental pulmonary fibrosis (PF) and subepithelial fibrosis in asthma." (PMID 37175437, 2023). "In asthma, airway inflammation can be suppressed by peroxisome proliferator‐activated receptor‐alpha (PPAR‐α) agonists as it reduces the release of inflammatory mediators majorly involved in asthma." (PMID 36348778, 2022). "In fact, the modulation of PPARα expression by inhibitor or activator molecules leads to significant consequences for asthma." (PMID 34445677, 2021). "Regarding the significance of ADPN modulation of PPARs in asthma, it is notable that PPARα and PPARγ expressions are upregulated in the lung tissue of OVA-challenged obese mice." (PMID 34445677, 2021). "A study of the leukocyte methylome in asthma patients detected PPARα pathway enriched in differentially methylated regions, but the study design did not permit identification of the specific cell types affected." (PMID 34638914, 2021). "This might be the reason why lobeglitazone, which has the benefits of activating both PPARα and PPARγ, had such extensive effects on asthma (reduction in inflammatory infiltrate, hyperresponsiveness, mucus secretion)." (PMID 34445677, 2021). "On the physiological side, follow-up studies will have to demonstrate a predicted improved therapeutic benefit may take place, when co-administering GCs and PPARα agonists in an animal model of chronic inflammation (e.g., multiple sclerosis, arthritis, or asthma)." (PMID 31447832, 2019). "It was suggested that this PPARα deletion worsened eosinophilia and asthma-like symptoms by preventing the anti-inflammatory actions mediated by the endogenous PPARα ligand, LTB4, known to be produced abundantly by mast cells and other cell types in asthma." (PMID 18000530, 2007).